FOXP3 (forkhead box P3)
Diseases named in the same sentence as FOXP3 in open-access papers (continued):
Sharing a sentence is not in itself a finding about the gene and the disease.
colitis (continued). "Although TRAF6-deficient Tregs possess similar in vitro suppression activity compared to wild-type Tregs, TRAF6-deficient Tregs did not suppress colitis in lymphopenic mice very efficiently due to reduced number of Foxp3-positive cells." (PMID 24058613, 2013). "In contrast, Mst1-/- Foxp3+ Treg cells were not able to prevent colitis and showed a similar degree of the body weight loss as mice that received only naïve T cells." (PMID 24040101, 2013). "Moreover, PPAR-gamma agonist-induced Treg cells maintain a high level of Foxp3 expression, and deficiency of PPAR-gamma in T cells accelerates the onset of colitis and decreases the number of Treg cells." (PMID 23776564, 2013). "In addition, co-transfer of Nod2 deficient activated/memory CD4+CD45RBlow T cells prevented the induction of colitis and induced a development of Foxp3+ Treg cells comparable to the one observed after transfer of wild type T cells." (PMID 24324812, 2013). "We found severe colitis with inflammatory cell infiltration in DTx-treated Foxp3-GFP-DTR mice." (PMID 22849659, 2012). "Moreover, IL-10 secreted by CD11b+CD11c+ dendritic cells is a fundamental cytokine for the maintenance of Foxp3 expression in induced regulatory T cells in the periphery during colitis development." (PMID 22400037, 2012). "The specific deletion of IL-10 in Foxp3+ T reg cells in mice induces inflammation especially in the intestine, indicating that IL-10 derived from T reg cells plays a critical role in controlling colitis." (PMID 21533081, 2011). "In this study, we address the hypothesis that colitis in Gαi2−/− mice is a consequence of a qualitative or quantitative defect in CD4+FoxP3+ regulatory T cells (Treg)." (PMID 21966415, 2011). "Furthermore, M. Kronenberg and his colleagues recently found that IL-10 secreted by other cells is needed for T reg cells to sustain expression of Foxp3 and prevent colitis." (PMID 21533081, 2011). "Indeed, we found that protection of ILK-ko mice from colitis correlated with a relative increase in Foxp3+ Tregs in both the colon and in mesenteric lymph nodes." (PMID 21806815, 2011). "IL-10 production by Foxp3+ T reg cells is required for the prevention of colitis." (PMID 21533081, 2011). "However, we found that B6 WT CD4+CD25+Foxp3+ Treg efficiently suppressed T-cell-mediated colitis in both B6.RAG−/− or B6.RAG−/−.TLR2−/− recipients." (PMID 19950179, 2010). "The fact that Foxp3-deficient T cells can induce high levels of colitis in the absence of IL-23 provides direct evidence that IL-23 is not essential to the pathogenesis of intestinal inflammation, if regulation is absent." (PMID 18400195, 2008). "Foxp3-deficient T cells induced colitis when transferred into recipients lacking IL-23p19, showing that IL-23 was not essential for intestinal inflammation in the absence of Foxp3." (PMID 18400195, 2008). "We therefore hypothesized that the FoxP3+ population might be related to the resistance to colitis observed in Il23a−/−Rag1−/− mice." (PMID 18400195, 2008). "IFN-γ can also have immunomodulatory effects on antigen-presenting cells and a recent report has demonstrated that adoptive transfer of IFN-γ-stimulated monocyte-derived cells promotes the resolution of experimental colitis and is associated with an enrichment of CD25+ Foxp3+ T cells." (PMID 18792404, 2008). "The content of IL-10 in culture supernatant was measured by an enzyme-linked immunosorbent assay (ELISA), and CD4+Foxp3+ Treg cells were sorted and adoptively transferred (40,000 cells/mouse) via tail vein injection into C57BL/6 J mice, followed by DSS administration to induce acute colitis." (PMID 40597393, 2025). "Since the decreased intestinal expression of Foxp3, which occurs in IBD and experimental colitis, can impair the intestinal immune tolerance and activate inflammation, it can be assumed that preventing the reduction in Foxp3 expression may alleviate intestinal inflammation." (PMID 36077306, 2022).
colitis (continued). "Loss of IL-10 production by Foxp3+ Tregs has been correlated with disease progression in a NOD model of type 1 diabetes, and disruption of IL-10 expression in Foxp3+ Tregs led to spontaneous colitis and augmented immune-response related inflammation in the skin and lungs of mice." (PMID 36466912, 2022). "However, based on these previous studies, the role of DN iNKT cells in balancing the ratio of Foxp3+CD25+ Treg cells to Foxp3−CD25+CD4+ T cells during the pathogenesis of colitis remains largely unknown." (PMID 36499642, 2022). "Further, TLA1 modulates Foxp3 expression in Tregs and its function, and murine model of colitis has seen the alleviation of colitis when treated with Tregs expressing low levels of TLA1.TLA1 may promote the maintenance of Treg suppressor function in a death domain receptor 3 (DR3) dependent manner." (PMID 34440615, 2021). "Indeed, inhibition of HDAC increased FOXP3 expression and Tregs numbers enhanced the suppressive function of FoxP3+ Tregs under homeostatic conditions and amplified Tregs cell-mediated attenuation of colitis in mice." (PMID 33922797, 2021). "To further define the key role played by Foxp3+CD4+Treg cells in the exacerbated inflammatory response of Lgals1−/− mice to DSS-induced colitis, we assessed whether adoptive transfer of WT Foxp3+CD4+Treg cells could reverse the enhanced inflammatory response observed in colitic Lgals1−/− mice." (PMID 34262567, 2021). "However, levels of Foxp3, inflammation-induced cytokines, and co-stimulatory molecules were comparable to WT animals or even slightly decreased, which is consistent with the slightly decreased colitis severity." (PMID 34201918, 2021). "However, the increased expression of CTLA4 was observed only in CD4+Foxp3+ T cells in colitis." (PMID 34336843, 2021). "In conclusion, TOE could alleviate chronic colitis via upregulation of Foxp3+ Treg cells and production of the anti-inflammatory cytokine IL-10, which directly inhibits macrophages and pro-inflammatory cytokine synthesis, leading to reduced colitis." (PMID 33092149, 2020). "Interestingly, class IIb HDACs are only involved Foxp3 destabilization, as shown in cystic fibrosis, collagen-induced arthritis, juvenile idiopathic arthritis, and lupus prone mice, as well as in cardiac allograft transplantation and colitis." (PMID 32235291, 2020). "In addition, the population of CD4+CD25+Foxp3+ Tregs in the peripheral blood was significantly upregulated in the pretreated-Bifico-colitis and pretreated + treated-Bifico-colitis groups compared with the colitis group (P < 0.05 for both)." (PMID 29849501, 2018). "Moreover, GW9662 weakened the downregulation of Th17 cell-specific cytokine expression and the upregulation of IL-10 expression by madecassic acid in the colons and diminished madecassic acid-induced upregulation of Foxp3 expression and protection against colitis." (PMID 28358365, 2017). "Interestingly, the macrophage migration inhibitory factor (MIF) homolog from Anisakis simplex (As-MIF) has also been shown to induce upregulation of IL-10 in both lymph node and intestinal epithelial cells, and also increases Foxp3+ Treg expression in mice subject to DSS-induced colitis." (PMID 28302598, 2017). "This suggests that IPEX-associated colitis results from autoimmune attacks rather than from defects in tolerance to the microbiota and, thus, that mechanisms other than Foxp3 Treg-dependent suppression, possibly including suppression by DP8α Tregs, are involved in human colonic homeostasis." (PMID 26500657, 2015). "However, most mouse models showing prevention or cure of colitis with Foxp3+ Treg have been conducted in lymphopenic animals, in which homeostatic expansion of Foxp3+ Treg may facilitate their impact on disease." (PMID 22849659, 2012). "Indeed, protection of colitis seen after transfer of naïve T-cells to RAG mice lacking IL-23 was associated with an increase in the frequency of Foxp3-expressing T regulatory cells in the intestine." (PMID 19503799, 2009).
colitis (continued). "Notably, transfer of Foxp3-deficient T-cells to IL-23-deficient RAG mice caused severe colitis, indicating that IL-23 is not essential to the pathogenesis of intestinal inflammation, if counterregulatory mechanisms are defective or absent." (PMID 19503799, 2009). "Using a mouse model of colitis, researchers showed that HDAC9 knockout increases both the number and suppressive capacity of Foxp3+Tregs, partly by preserving Foxp3 acetylation status." (PMID 41416997, 2025). "In a dextran sulfate-induced colitis model, YY1 was shown to reduce Foxp3 expression in Tregs, thereby inhibiting their suppressive function." (PMID 40458393, 2025). "Consistently, the transcript levels of Ifn‐γ, Tbx21 and Tnf‐α were elevated while Foxp3 and Il10 levels were decreased of TNBS‐induced Atg7ΔCD4 colitis mice relative to littermate controls born with Atg7fl/fl." (PMID 40887825, 2025). "Our study provides compelling evidence that ACC1 inhibition during iTreg differentiation enhances their stability and FoxP3 retention, even after adoptive transfer in models of inflammatory diseases such as EAE and colitis." (PMID 39929287, 2025). "Here, the DSS-induced colitis mice showed a remarkable imbalance with a significant increase in CD4+CCR6+ Th17 cells and a significant decrease in CD4+Foxp3+ Treg cells in the mesenteric lymph nodes (MLNs)." (PMID 38202824, 2024). "Furthermore, the intestinal CD4+Foxp3+RORγt+ Treg cells induced by gut microbiota have been shown to contribute to the suppression of gut inflammation, the inhibition of TH2-driven defense against helminths and TH2-associated colitis, and the inhibition of intestinal TH2-associated allergy." (PMID 39206204, 2024). "The new Foxp3‐tdTomato‐IL17−EGFP mouse strain is a good tool for simultaneously monitoring Tregs, Th17 cells, and Treg/Th17 cells in not only colitis but other disorders." (PMID 38415949, 2024). "We determined the frequencies of Tregs (CD4+FOXP3+), Th1 cells (CD4+CXCR3+), and Tfh cells (CD4+CXCR5+) in the colonic lamina propria in DSS-induced colitis." (PMID 38396052, 2024). "In contrast, Foxp3 mRNA in SASP and L-Alb, H-Alb groups were increased compared with DSS induced colitis mice (P<0.01 or P<0.05)." (PMID 36594064, 2023). "Albiflorin enhanced the expression levels of Foxp3 and STAT5 in colon, decreased adrenodoxin, NF-κB, and TLR4 mRNA with the increase of Foxp3 mRNA in colitis." (PMID 36594064, 2023). "In experimental colitis and graft versus host disease (GVHD) mice, the researchers found that programmed cell death ligand 1 (PD-L1) maintains the intrinsic function of Foxp3 by specifically lowering the AEP in lysozyme." (PMID 36609651, 2023). "Certainly, T cell specific deletion of Hif1α significantly downregulates Foxp3 over IL-17 expression, leading to the uncontrolled immune responses in DSS-induced colitis model." (PMID 37809060, 2023). "VDR favors FoxP3+ T reg cells, which prevent the development of experimental colitis through the production of inhibitory cytokines such as IL-10 and TGF-β and FoxP3+ T reg cells are induced by 1,25(OH)2D3 treatments in vitro and in vivo." (PMID 35057450, 2022). "Depletion of either CD11c+ dendritic cells or Foxp3+ regulatory T cells ablated AIP-2-induced protection against asthma and Na-AIP-1-induced protection against colitis." (PMID 36186812, 2022). "Similar results are observed in a separate report, in which Odoribacter splanchnicus colonization leads to an increase in Foxp3+/RORγt+ Treg cells, induction of IL-10, and production of SCFA, thus reducing colitis in mouse models." (PMID 35967333, 2022). "Treatment with analogue 5 elevated the percentage of CD25+FoxP3+ Treg in MLN CD4 lymphocytes of mice with TNBS- and DSS-induced colitis." (PMID 33767180, 2021).
colitis (continued). "In DSS-induced colitis, THC or THC+CBD treatments reduce polyps in colon cancer-induced mice and increase CD103+ dendritic cells and CD4+Nrp1+FoxP3+ T regulatory cells (nTregs) in the lamina propria through activation of the CB2 receptor." (PMID 34298921, 2021). "In this study, we investigated the change of Foxp3+ Treg cell frequencies in lymphoid organs and colon tissue after treatments of the primed or unstimulated MSCs for DSS-induced colitis." (PMID 33413597, 2021). "Moreover, CDK2-deficient Tregs are more suppressive and ameliorate colitis in an in vivo mouse model of IBD; this is primarily because the N-terminal amino acid sequence of Foxp3, which contains four CDK substrate motifs and is phosphorylated by CDK2, leading to Foxp3 instability." (PMID 34759371, 2021). "The increase in the ratio of CD4+Nrp1+FoxP3+ cells in the lamina propria reduces disease severity in THC- and THC+CBD-treated colitis mice compared to VEH-treated colitis mice." (PMID 34298921, 2021). "We investigated the role of Foxp3, IL-10, and TGF-β in the suppression of colitis by epicutaneous immunotherapy (ET)." (PMID 33717186, 2021). "Foxp3 expression was also increased in the colon mucosa during acute and chronic DSS-induced colitis." (PMID 34178715, 2021). "Given that activation of CD4+/CD8+ T cells and FOXP3+ Tregs usually mediates pro-inflammatory and anti-inflammatory responses, respectively, alterations in the colonic numbers of these adaptive T cells might be related to the resolution of colitis in patients with CC." (PMID 34350195, 2021). "The SCFAs can also regulate the interactions between microbiota and immune cells with the mechanism of stimulating the IL-10 producing Foxp3+ Tregs via inhibiting HDAC, thereby alleviating colitis." (PMID 34917080, 2021). "Increased expression of Foxp3 was found in colonic tissue, with an increase in Foxp3+ Tregs in the MLN, suggesting a role for Tregs in reduction of TNBS-induced colitis." (PMID 34246032, 2021). "By gating CD4+ Foxp3+ cells we observed a moderate increase in frequencies and absolute number of Tregs in the colon upon DSS-induced colitis." (PMID 34335571, 2021). "Significantly, genetically or pharmacologically activating Hh signalling has been reported to ameliorate colitis by inducing the expression of IL-10 in Hh-responsive stromal cells, which subsequently increases the amount of CD4+Foxp3+ regulatory T cells." (PMID 34702800, 2021). "To first evaluate the role of IL-33-mediated Treg expansion on the course of DSS-induced colitis, we used DEREG/c mice to specifically deplete Foxp3+ Tregs by applying diphtheria toxin (DT)." (PMID 34335571, 2021). "Alpinetin, a flavonoid, was found to suppress colitis through upregulation of miR-302 and decreasing the expression of DNMT-1, and thereby the methylation of FoxP3 promoter in CD4+ T cells in mice, leading to the induction of Tregs." (PMID 33105907, 2020). "In a DSS-induced colitis mouse model, adipose tissue-derived MSCs expressed PGE2 which induced FOXP3 mRNA expression." (PMID 32256612, 2020). "B. fragilis PSA induces the differentiation of IL-10 producing FoxP3+ Tregs in mice in a TLR2-dependent manner, which can protect against TNBS-induced colitis and experimental colitis induced by Helicobacter hepaticus." (PMID 32351514, 2020). "The frequency of Th17 cells in the MLNs of experimental colitis mice decreased after injection of QCHS-treated DCs, whereas the frequency of CD4+CD25+Foxp3+ Tregs was upregulated." (PMID 32967687, 2020). "IL-2/JES6-1 immunocomplexes have been shown to induce rapid CD25+Foxp3+ Treg expansion in the spleen of mice and afford protection from dextran sodium sulfate (DSS)-induced colitis when delivered for one week prior to the initiation of DSS." (PMID 30930900, 2019).
colitis (continued). "A previous report elegantly demonstrated that IL-2/JES6-1 immunocomplexes are effective at expanding Foxp3+ T cells in the spleens of mice and when delivered for 1 week prior to the initiation of DSS were able to lessen colitis." (PMID 30930900, 2019). "In the mouse model of trinitrobenzene sulfonic acid (TNBS)-induced colitis, dextran sulfate sodium (DSS)-induced colitis or T cell adoptive transfer induced colitis, IL-33 can increase the number of Foxp3+ Tregs." (PMID 30761089, 2019). "The identification of a decrease in Foxp3+ expressing Tregs in peripheral blood and MLN in acute colitis followed by a recovery phase and increase above normal levels in chronic DSS colitis are in line with the findings in human IBD38." (PMID 31296924, 2019). "C/EBPβ-transduced Treg cells express higher level of Foxp3, display an increased suppressive function with subsequent improvement of EAE and colitis when transferred in mouse models of diseases." (PMID 32117202, 2019). "Together with the increased splenic and MLN complement of Foxp3+ Tregs, a significant tolerogenic state is established in vivo and this, along with the increase in B10 Bregs, could be a powerful suppressant of the most acute and damaging experimental model of colitis; DSS." (PMID 29774025, 2018). "In patients with either proctitis or left-sided colitis, the percentage of CD4+Foxp3+ cells was significantly higher in involved tissue than in uninvolved tissue." (PMID 30425718, 2018). "The frequencies of CD4+ CD25+ Foxp3+ and CD4+ CD25+ CD127− cells in the spleens from mice with DSS‐induced colitis were significantly down‐regulated by wogonin (100 mg/kg) treatment, compared with those in the solvent and DSS/solvent groups." (PMID 27641629, 2017). "In DSS-induced colitis model, the pretreatment of mice with Hsp65-LL increased the CD4+Foxp3+ cell frequency in the spleen when compared to naïve mice after 3 days of colitis induction." (PMID 28194152, 2017). "In this study, we showed that oral administration of Hsp65-LL prevented colitis development in mice and induced CD4+Foxp3+/CD4+LAP+ Tregs in a TLR2/IL-10-dependent fashion." (PMID 28194152, 2017). "Here the authors show that IL-15 promotes Foxp3 and inhibits RORγt expression in CD4 T cells, and that IL-15 is critical to suppress colitis by maintaining the Treg to Th1/Th17 ratio in a mouse model." (PMID 26964669, 2016). "The E-cadherin-treated BM-DCs induced gut-tropic Foxp3+ T cells and alleviated DSS–induced colitis, whereas the TLR-L-treated DCs aggravated DSS–induced colitis." (PMID 27897208, 2016). "Foxp3, the marker of regulatory T cells (Tregs), was enhanced in both TNBS- and oxazolone-induced colitis after VD treatment." (PMID 27620138, 2016). "During DSS-induced colitis, CCR7KO mice showed a higher percentage of Foxp3+CD4+ Tregs in every tissue sampled than the WT mice." (PMID 26908454, 2016). "Plasma levels of IL-6 in the colitis group were significantly higher than those in the control group, which was consistent with the results of the CD25 + Foxp3+ Treg analysis in rat peripheral blood cells." (PMID 27473867, 2016). "We found that CD25+ and CD25− Foxp3+CD4+ Tregs showed similar tendency as Foxp3+CD4+ Tregs during both, steady state and colitis conditions." (PMID 26908454, 2016). "In the mouse-TNBS colitis model, oral administration of Imm124E increased serum levels of the anti-inflammatory cytokine IL-10 and promoted both CD4+CD25+ and CD4+Foxp3+ Tregs." (PMID 26900473, 2016). "Consistently with the enlargement of the Foxp3+ TREG pool in the colon, mice fed with a fiber enriched diet showed decreased T cell transfer-mediated colitis, which depends on a direct effect of SCFA on Foxp3+ TREG rather than de novo Foxp3+ TREG generation." (PMID 26347740, 2015). "By contrast, IP injection of NAC significantly reduced the frequency of FoxP3+ cells and aggravated inflammatory reaction in the lesions of DSS-induced colitis." (PMID 24743300, 2014).